CCL3 (C-C motif chemokine ligand 3)
Description:
Monokine with inflammatory and chemokinetic properties. Binds to CCR1, CCR4 and CCR5. One of the major HIV-suppressive factors produced by CD8+ T-cells. Recombinant MIP-1-alpha induces a dose-dependent inhibition of different strains of HIV-1, HIV-2, and simian immunodeficiency virus (SIV).
Synonyms: MIP-1-alpha; G0S19-1; MIP1A; SCYA3; LD78ALPHA; LD78; SCI
Tractability: Antibody: its Gene Ontology location is reachable by antibodies, with high confidence; UniProt places it where antibodies can reach, with medium confidence; UniProt predicts a signal peptide or a membrane-spanning region.
Gene: Protein-coding gene on chromosome 17 (36,088,256 to 36,090,169, reverse strand). Ensembl gene ENSG00000277632.
Subcellular location: Secreted
Pathways (Reactome):
Developmental Biology: Differentiation of naive CD4+ T cells to T helper 1 cells (Th1 cells)
Immune System: Interleukin-10 signaling
Signal Transduction: Chemokine receptors bind chemokines
Gene Ontology:
Molecular function: CCR1 chemokine receptor binding; CCR5 chemokine receptor binding; chemoattractant activity; chemokine activity; identical protein binding; kinase activity; phospholipase activator activity; protein binding; protein kinase activity; CCR chemokine receptor binding
Biological process: calcium ion transport; calcium-mediated signaling; cell activation; cell-cell signaling; cellular response to interleukin-1; cellular response to tumor necrosis factor; cellular response to type II interferon; chemotaxis; cytoskeleton organization; eosinophil chemotaxis; eosinophil degranulation; exocytosis; granulocyte chemotaxis; host-mediated suppression of viral transcription; inflammatory response; intracellular calcium ion homeostasis; lymphocyte chemotaxis; MAPK cascade; monocyte chemotaxis; negative regulation of bone mineralization; negative regulation of gene expression; negative regulation of osteoclast differentiation; neutrophil chemotaxis; osteoblast differentiation; positive regulation of calcium ion transport; and 28 more
Cellular component: cytoplasm; cytosol; extracellular region
Genetic constraint (gnomAD): Loss-of-function variants: 8 observed, 10.7 expected, observed/expected ratio (o/e) 0.75, 90% interval 0.44 to 1.35. The upper end of that interval is the gene's LOEUF score, 1.35, which puts it in group 5 of 6, group 1 being the genes least tolerant of losing a copy. Missense variants: 109 observed, 120.05 expected, observed/expected ratio (o/e) 0.91, 90% interval 0.78 to 1.07. Synonymous variants: 45 observed, 47.25 expected, observed/expected ratio (o/e) 0.95, 90% interval 0.75 to 1.22.
Homologues: Orthologues: chimpanzee CCL3 (97% identical), macaque CCL3 (89% identical), rat Ccl3 (77% identical), mouse Ccl3 (76% identical), pig CCL3L1 (76% identical), dog CCL3 (71% identical), zebrafish ccl35.1 (34% identical), zebrafish ccl35.2 (34% identical). Paralogues in human: CCL3L3 (96% identical), CCL18 (61% identical), CCL4 (58% identical), CCL4L2 (52% identical), CCL23 (49% identical), CCL5 (48% identical), CCL15 (47% identical), CCL14 (45% identical), CCL13 (37% identical), CCL16 (37% identical), CCL8 (37% identical), CCL11 (36% identical), and 14 more.
Diseases named in the same sentence as CCL3 in open-access papers:
CCL3 is named in the same sentence as 575 diseases in open-access papers, as found by Europe PMC text mining. Sharing a sentence is not in itself a finding about the gene and the disease. The quoted sentences say what the papers report.
COVID-19 (385 papers, 2020 to 2026). A disease caused by infection with severe acute respiratory syndrome coronavirus 2. "Alveolar macrophage (Mph) CCL3+ cells were associated with COVID-19 (FDR = 0.020), in line with pro-inflammatory monocyte-derived alveolar infiltration during acute infection." (PMID 41463538, 2025). "The COVID-19-associated CCL3+ macrophage subclusters showed two distinct functional programs—Group A displaying surfactant-associated and innate-immune signatures and Group B characterized by stress-response and antigen-presentation genes." (PMID 41463538, 2025). "We observed pronounced cellular heterogeneity in the association between alveolar Mph CCL3+ cells and COVID-19." (PMID 41463538, 2025). "While further limited by the small number of PLWH with severe illness, interaction models also suggested that higher concentrations of IFN-α2, IL-6, CCL3, IL-1a, and IL-1Ra were associated with more severe COVID-19 in PLWH." (PMID 38368384, 2024). "In COVID-19, CCL3 was statistically positively associated with T cells CD8 but negatively with mast cells resting and macrophages M0." (PMID 36531995, 2022). "We found that alveolar type II (AT2) cells represent a central susceptibility hub for asthma, COPD, and COVID-19, whereas disease-specific risk enrichment was observed in subpopulations such as CCL3+ alveolar macrophages in COVID-19 and adventitial fibroblasts in asthma." (PMID 41463538, 2025). "Among immune cells, alveolar macrophages (Mph) CCL3+ showed heterogeneity in their association with COVID-19 (FDR = 0.010), whereas proliferating alveolar macrophages exhibited heterogeneous associations with IFA, IPF, and PAH (FDRIFA = 0.020, FDRIPF = 0.047, FDRPAH = 0.034)." (PMID 41463538, 2025). "Patients with PS or LC show persistent systemic inflammation 12 months after the acute COVID-19 episode, but CCL3 and CCL19 are specifically associated with PS, and the deterioration of DLCO in these patients, whereas LC patients present increased circulating levels of organ-damage markers." (PMID 40247373, 2025). "First, we studied the profile of different soluble pro-inflammatory cytokines (GM-CSF, TNF-α, IFN-γ, IL-1β, IL-2, IL-6, IL-7, IL-10, IL-17A, IL-21) and chemokines mediating monocyte and neutrophil recruitment (IL8, CCL3), whose exacerbated production is associated with severe COVID-19." (PMID 36675231, 2023). "Furthermore, COVID-19 caused excessive production of proinflammatory cytokines such as IL-6, IL-2, IL-7, granulocyte-colony stimulating factor (G-CSF), Macrophage Inflammatory Protein-1 Alpha ((MIP-1-α)/CCL3, and TNF-α), termed as cytokine storm." (PMID 37377785, 2023). "We observed a trend toward increased CCL2 levels with the outcomes of the COVID-19 patients, as well as, of IL-1Ra and CCL3 levels being elevated in patients with severe disease." (PMID 40881695, 2025). "Although concentrations of many mediators were similar across SARI etiology, those reflective of neutrophil chemotaxis and Th17 pathways (IL-8, CCL3, IL-17E) were significantly higher in patients with COVID-19." (PMID 38368384, 2024). "For example, one study showed that CCL3 is elevated in patients with more severe COVID-19 symptoms in monocytes sampled from PBMCs33." (PMID 39627184, 2024). "Vector analysis conducted in the 1st trimester indicated that CXCL8, CCL3, CCL5, IL-1β, TNF-α, IL-12, IL-15, IL-1Ra, IL-10, and G-CSF were associated with convalescent COVID-19 in pregnant women." (PMID 37122732, 2023). "It has been reported that CCL3 expression is higher in COVID-19 patients with an unfavorable outcome." (PMID 36993968, 2023).
COVID-19 (continued). "A recent observation showed that macrophages and neutrophils from hypertension patients with COVID-19 exhibited higher expression of the proinflammatory cytokines CCL3 and CCL4 and the chemokine receptor CCR1." (PMID 37198402, 2023). "More importantly, the results presented herein prove that vitamin B12 downregulates CCL3 in leukocytes of patients with moderate or severe COVID-19 via the hypermethylation of CpGs and subsequent inhibition of TF binding to the analyzed regulatory region." (PMID 36993968, 2023). "Another interesting finding was the increased serum levels of IL-1β, IL-3, IL-17, and CCL3 in severe COVID-19 exclusively." (PMID 37373331, 2023). "Several chemokines linked to COVID-19 were also significantly induced by the S1 subunit, including CCL3/MIP-1α, CCL4MIP-1β, and CXCL10/IP-10." (PMID 35392091, 2022). "Mon HLA and Mon CD14 inside Delta samples differ in expression for the cytokine panel (CCL3, VEGFA, CCL5, CCL4, CXCR4, IL7R, CXCL8, and PF4) that have been found associated with COVID-19 severity and mortality." (PMID 36230912, 2022). "Neutrophils play a significant role in COVID-19 severity, as CCL3 is upregulated in severe COVID-19." (PMID 36510222, 2022). "We observed increased expression of CCL13, CCL3, CXCL11 and CXCL10 which were associated with severe COVID-19 outcome in humans." (PMID 36298826, 2022). "In symptomatic or asymptomatic COVID-19, the CCL3, CCL4, and CCL5 chemokines were detected in a similar fashion." (PMID 36016187, 2022). "In our cohorts, the levels of MIP chemokines CCL3/MIP-1α and CCL4/MIP-1β, although exceeding the numbers found in the healthy donors’ cohort, varied depending on the COVID-19 severity and virus genetic variant." (PMID 36012323, 2022). "Of the 16 mediators elevated in early COVID-19 compared with healthy controls, 11 decreased over time (CCL3, CCL4, TNF-α, IL-6, CCL13, IL-4, IFN-α2a, CXCL10, CXCL11, IL-2, and IL-12)." (PMID 35397798, 2022). "The majority of upregulated cytokines and chemokines, such as IL-6, TNF, CCL2, CCL3, and CXCL10, have been reported to be associated with cytokine release syndrome (CRS), including MAS, in severe COVID-19 cases." (PMID 35440562, 2022). "This study also found that LTBI/COVID-19 versus COVID-19 patients had higher levels of CCL3 and CXCL10 chemokines, which are critical for T cell migration and Th1 immune response." (PMID 36090983, 2022). "In this regard, it has been discussed that high production of some chemokines, such as CXCL8/IL-8, CCL-2/MCP-1, CCL3, CCL5, CXCL9, and CXCL10 are associated with lung damage and COVID-19 severity." (PMID 36685603, 2022). "COVID-19 patients have been shown to have higher levels of chemokines such as CCL3, CCL5, CXCL10, CCL19, CCL20, while CCL5 remained unchanged." (PMID 35782361, 2022). "Meanwhile, hyperinflammation associated with severe COVID-19 also encompasses the release of inflammatory chemokines such as CCL2, CCL3, and IP-10." (PMID 35647937, 2022). "At later stages, they found a persistent inflammatory phenotypein patients with severe COVID-19, dominated by high CCL3 and CCL4cytokine abundance correlated with the reappearance of CD16+ monocytes,while the response of mild COVID-19 patients was normalized." (PMID 35940589, 2022). "IL-8 and CCL3 which have been reported as COVID-19 severity markers and TNF-β was found in less severe disease, which is in agreement with our findings." (PMID 35479098, 2022). "MIP 1-α is associated with COVID-19 and, therefore, targeting MIP 1-α directly or altering it at the receptor level (CCL3 blocker) represents a wise approach to managing COVID-19." (PMID 34063739, 2021). "IL-33, MCP-1/CCL2, and MIP-1α/CCL3 were also elevated in ICU status COVID-19 subjects over controls, consistent with other reports." (PMID 34960684, 2021).
COVID-19 (continued). "They identified neutrophils (IFITM2, IFITM1, H3-H3B, SAT1 and S100A8) and macrophage cluster-1 (CCL8, CCL3, CCL2, KLF6 and SPP1) as the main immune cell subsets associated with severe COVID-19 cases." (PMID 34109284, 2021). "Of the significantly dysregulated cytokines in both COVID-19 and CAD, pro-inflammatory cytokines CCL3 and CCL4 have been associated with COVID-19 severity." (PMID 34071557, 2021). "These cytokines, such as IL-6, IL-7, CCL-2/MCP-1, CCL-3/CCL-4 MIP-1α/β, TNF-α, and G-CSF, have been implicated in COVID-19 pathogenesis." (PMID 34341347, 2021). "In contrast, the highest contributors to dimension 1 were IL-21, IL-2, IL-1b, IL-17A, GM-CSF, IFN-γ, IL-7 and CCL3, and these cytokines were significantly decreased in acute COVID-19 patients in comparison to HC." (PMID 34572439, 2021). "Our data show increased cytokine and chemokine gene expression, including CXCL8, IL-1β, and CCL3 (MIP-1α) in both mild and severe COVID-19, compared to healthy controls." (PMID 34108966, 2021). "Cytokine-related genes that were found to be dysregulated in both CAD patients and COVID-19 patients include chemokines (CCL3 and CCL4), chemokine receptor CXCR1, and a TNFSF gene, LTB." (PMID 34071557, 2021). "Their results revealed host inflammatory cytokine profiles to SARS-CoV-2 infection in patients and highlighted the association between COVID-19 pathogenesis and excessive cytokine releases such as CCL2/MCP-1, CXCL10/IP-10, CCL3/MIP-1A, and CCL4/MIP1B." (PMID 34441862, 2021). "Among the identified gene signatures, IFITM2, IFITM1, H3F3B, SAT1, and S100A8 gene signatures were highly associated with neutrophils, while CCL8, CCL3, CCL2, KLF6, and SPP1 were associated with macrophage cluster-1 in severe-COVID-19 patients." (PMID 33138195, 2020). "Our results reveal distinct host inflammatory cytokine profiles to SARS-CoV-2 infection in patients, and highlight the association between COVID-19 pathogenesis and excessive cytokine release such as CCL2/MCP-1, CXCL10/IP-10, CCL3/MIP-1A, and CCL4/MIP1B." (PMID 32228226, 2020). "The cytokine profile of sHLH is associated with the severity of COVID-19, which is characterized by increased interleukin (IL)-2, IL-7, GCSF, IP10 (CXCL10), MCF1 (CCL2), MIP1A (CCL3), and TNF-α." (PMID 32574260, 2020). "Higher levels of several inflammatory cytokines including TNF-α, IL-6, and IL-1 and inflammatory chemokines such as CCL2, CCL3, and CXCL10 are associated with disease severity and death in COVID-19 patients." (PMID 33138195, 2020). "Similarly, CXCL-10 showed the highest concentration in the deceased group, and IL-1Ra and CCL3 also presented the highest concentrations in the severe and deceased COVID-19 groups." (PMID 40881695, 2025). "This decline in CCL2 and CCL3 might revert T cell exclusion and the cytokine storm thereby affecting COVID-19 severity." (PMID 40055791, 2025). "In post-COVID-19 patients, CCL3 was found to maintain higher expression than in healthy controls." (PMID 39407208, 2024). "As expected, performing TPE decreased the amount of anti-type I IFN auto-antibodies and improved the elimination or limited the production of certain inflammatory mediators (IL-18, IL-7, CCL2, CCL3, etc.)circulating in the blood of COVID-19 patients, compared to ST controls." (PMID 39896810, 2024). "We observe that the specificity of CCL3 expression further suggests that CCL3 may be released by only a subset of monocytes in patients with severe COVID-19." (PMID 39627184, 2024). "Severe cases of COVID-19 are associated with prolonged, heightened levels of cytokines, such as IL-6, IL-8/CXCL8, CXCL9, CXCL10, TNF-α, MCP1/CCL2, RANTES/CCL5, IL-18, and MIP-1α/CCL3, which can last for up to two months." (PMID 36983995, 2023). "Therefore, the severe form of COVID-19 induces hypomethylation of a CpG locus in the regulatory region of CCL3, which is coherent with its upregulation." (PMID 36993968, 2023).
COVID-19 (continued). "BAL alveolar macrophages from severe COVID-19 patients (n = 23) were characterized by an increased production and release of several pro-inflammatory mediators, such as IL-1β, IL-6, CCL3 and CCL4 and increased expression of IL-1R and S100A8/9 proteins, compared to those from mild COVID-19 patients." (PMID 36941580, 2023). "According to the literature, higher levels of CCL2 and CCL3 also play a role in COVID-19 severity." (PMID 37908356, 2023). "The cytokine storm phenomenon is an increase in pro-inflammatory cytokine levels in the serum, such as IL-2, IL-6 and IL-1β, IL-17, IL-8, G-CSF, GM-CSF, IP10, MCP1, MIP1α (also known as CCL3), and TNF, and causes acute respiratory distress syndrome (ARDS) in severe COVID-19 cases." (PMID 37626992, 2023). "However, some cytokines, including IL-1β, IL-3, IL-17, and CCL3, were uniquely activated in severe COVID-19." (PMID 37373331, 2023). "COVID-19 outcomes were found to be adverse for CCL3 and IL1B." (PMID 36225326, 2022). "To sum up, FCGR3A, TNF, and CCL3 might be potential biomarkers for COVID-19-related CU, and the common pathways and related molecules we explored in this study might provide new ideas for further mechanistic research." (PMID 36531995, 2022). "The earliest reports of COVID-19 clarified that IL-1β, IL-6, TNFα, and CCL3 in the peripheral blood of patients with severe COVID-19 pneumonia were significantly higher than those of non-severe patients, and this cytokine storm is an important factor contributing to death from COVID-19." (PMID 35120332, 2022). "In addition, we identified a group of EGR1+ monocytes which can differentiate into pro-inflammatory CCL3+ monocytes, indicating the potential sources of systemic inflammation in COVID-19 patients." (PMID 36379915, 2022). "Cytokine-related genes that are dysregulated in both cardiomyopathy patients and COVID-19 patients include chemokines (CCL3, CCL4, CXCL4, etc.), interleukins or interleukin receptors (IL15, IL20RA, etc.), and genes in the transforming growth factor beta (TGFB) family." (PMID 34071557, 2021). "Interestingly, the gene encoding FOS was downregulated in the SEV group at endpoint B compared to controls at endpoint A (contrast 4), indicating that B12, in addition to blocking the binding of this TF to the regulatory region of CCL3, also reduces its expression in severe COVID-19." (PMID 36993968, 2023). "These indicated that FCGR3A, TNF, and CCL3 might be the key genes of COVID-19-related CU." (PMID 36531995, 2022). "Previous studies reported that COVID-19 is frequently associated with a massive production of 14 cytokines including IFN-γ, IL-1RA (IL1RN), IL-2RA, IL-6, IL-10, IL-18, HGF, MCP-3 (CCL7), MIG (CXCL9), M-CSF (CSF1), G-CSF (CSF3), MIG-1a (CCL3), CTACK (CCL27), and IP-10 (CXCL10)." (PMID 34262555, 2021). "The aim of this work was to evaluate the associations of polymorphisms in the TNF-α, IL-6, IL-8, IL-10, CCL5 and CXCL6 genes with COVID-19 outcomes and with the serum levels of IFN-α, IFN-γ, TNF-α, IL-1Ra, IL-6, IL-7, IL-10, CCL2, CCL3, CXCL8, CXCL10 and GCSF." (PMID 40881695, 2025). "Genes in the subnetwork of the CCL family showed different expression levels in the four groups of COVID-19 severity; in particular, OSM, CCL3, CCL7, and IL2RA showed higher expression in the high-severity COVID-19 samples." (PMID 40362649, 2025). "In COVID-19, severe outcomes have increased levels of pro-inflammatory and anti-inflammatory cytokines and chemokines, such as IL-6, TNF-α, IL-10, CCL2, CCL3, CXCL8, and CXCL10, among others." (PMID 40881695, 2025). "Supervised machine learning algorithm (RF) was used to predict the COVID-19 severity and chronicity based on immune subset profiling and a 14-plex cytokine panel (TNF-a, IL-4, IL-13, IL-2, GM-CSF, sCD40L, CCL5, CCL3, IL-6, IL-10, IFN-g, VEGF, IL-8, and CCL4." (PMID 40657638, 2025).